EPO (erythropoietin)
Diseases named in the same sentence as EPO in open-access papers (continued):
Sharing a sentence is not in itself a finding about the gene and the disease.
anemia (continued). "Current work has demonstrated that EPO is expressed throughout the body and may affect multiple biological functions even though EPO is presently approved by the Food and Drug administration for the purpose of treating anemia." (PMID 23109841, 2012). "Therefore, we hypothesized that monocytes, as cells involved in atherosclerosis, could function as biosensors of the systemic environment of CRS patients with anemia and of the effects of short-term EPO treatment." (PMID 22957013, 2012). "Leaving aside the mechanisms that could explain the distribution of EPO levels in this study, the results indicate that the utility of EPO to distinguish malaria-attributable severe disease is limited, at least, in settings with high prevalence of anemia among ill children." (PMID 21912616, 2011). "Moreover, ACE-011 has potential as a novel therapy for chemotherapy-induced anemia and may be an effective alternative to erythropoietin- (EPO-) based treatments." (PMID 22046572, 2011). "A univariate analysis of risk factors associated with late PTA showed that anaemia is significantly associated with not using EPO in pre-transplant period (p < 0.001), History of rejection was also associated with PTA (p = 0.003), eGFR (p < 0.0001) and long period from transplantation (p = 0.015)." (PMID 21827693, 2011). "Darbepoetin alfa is an ESA with a 3-fold longer half-life and greater in vivo biological activity than recombinant human erythropoietin, allowing less frequent dosing that may simplify anemia management in these patients, providing benefits to patients, care givers and health care providers." (PMID 21435267, 2011). "The renoprotective effect of erythropoietin (EPO) in CKD might be partially related to an attenuation of interstitial fibrosis and tubuloepithelial cell loss by improved oxygen supply and reduced oxidative stress via correction of anemia." (PMID 18335252, 2008). "As Hb level was associated with mortality, we questioned whether EPO dose, a physician-dependent component of anaemia control, was associated with mortality, regardless of Hb." (PMID 19077225, 2008). "Therefore, erythropoietin (Epo) gene transfer appears to be a promising alternative for severe anaemia treatment since it requires less frequent treatment repeat and may allow sustained Epo secretion and constant patient coverage." (PMID 18334017, 2008). "However, this fails to explain why not all patients with iron-deficiency anemia and elevated levels of erythropoietin present with thrombocytosis." (PMID 18380894, 2008). "Among Nn and Pn infants, the slope of the fitted regression line between log10 plasma EPO (U/L) and hemoglobin (i.e., the EPO response to anemia) was significantly negative at 6 weeks; this association remained at 3 months and 6 months but was only significant among the Pn infants." (PMID 16390553, 2006). "Additionally, this population demonstrated an elevated EPO response to anemia in a previous study." (PMID 15987387, 2005). "Finally, the production of erythropoietin itself in response to anaemia is inadequate." (PMID 12799626, 2003). "In these and/or other clinical trials in patients with gastric cancer receiving cytotoxic chemotherapy, it might also be of particular interest to try to define precisely the impact of correcting anaemia with erythropoietin in terms of quality of life and therapeutic outcome." (PMID 12085176, 2002). "These include dilutional anemia from aggressive fluid resuscitation and reduced RBC production due to impaired metabolism of folic acid, vitamin B12, iron, or decreased erythropoietin." (PMID 41510515, 2026). "Anemia prevalence increases with advanced CKD, primarily due to inflammation‐related processes: impaired erythropoietin (EPO) production and restricted iron availability for erythropoiesis." (PMID 41376433, 2026).
anemia (continued). "Stunting could impair the synthesis of Hb and red blood cells through mechanisms such as reduced erythropoietin production brought on by proinflammatory cytokines and inadequate consumption of vital nutrients such as iron, vitamins, and minerals, which exacerbates anemia." (PMID 40426817, 2025). "The following primary objectives were selected: First, to evaluate the efficacy of NBO in reducing anemia in CRC patients undergoing chemotherapy by measuring markers of erythropoiesis, such as EPO levels, HIF-1α, and complete blood counts." (PMID 40725749, 2025). "A major contribution to improving anemia therapy has been made by darbepoetin alfa, the first ESA to provide longer dose intervals than EPO molecules, epoetins alfa, and beta." (PMID 39958087, 2025). "Furthermore, these studies highlight that EPO administration might diminish the therapeutic efficacy of intravenous immunoglobulin (IVIg), a cornerstone of B19V infection treatment in post-transplant anemia." (PMID 41458512, 2025). "Erythropoiesis-stimulating agents (ESAs), such as darbepoetin-α and epoetin-α, are the guideline-recommended, first-line standard-of-care for the treatment of symptomatic anemia in patients with LR-MDS and serum erythropoietin (EPO) ≤ 500 U/L." (PMID 39572468, 2025). "Erythropoietin (EPO) is a glycoprotein hormone essential for red blood cell production and a cornerstone therapy for anemia, particularly in chronic kidney disease." (PMID 41012526, 2025). "With the progression of CKD, kidneys lose their capacity to generate erythropoietin (EPO), leading to anemia." (PMID 41179057, 2025). "Congestion-induced renal hypoxia exacerbates anemia, particularly in patients with coexisting chronic kidney disease (CKD), which leads to decreased EPO synthesis and increased hepcidin levels." (PMID 40278183, 2025). "Anemia is a frequent and clinically significant complication of CKD, arising from multiple factors such as reduced erythropoietin production, iron-restricted erythropoiesis, persistent inflammation, and tissue hypoxia." (PMID 41267729, 2025). "Reduced production of thrombopoietin (TPO) and, to a lesser extent, erythropoietin (EPO), also plays a role in the development of thrombocytopenia and anemia, respectively." (PMID 40095848, 2025). "Relative EPO deficiency is further evidenced by studies showing blunted EPO responses to anemia in CKD patients, where serum EPO levels fail to rise adequately in proportion to hemoglobin decline." (PMID 41383483, 2025). "Erythropoietin (ERFE) inhibition and transferrin-2 (TFR2) inactivation are also explored regarding their effects on anemia and iron overload." (PMID 41294841, 2025). "We demonstrated that erythropoietin (EPO), an FDA-approved treatment for anemia, modulates inflammation and promotes the transition of MΦs from an M1 to an M2 phenotype, enhancing phagocytosis." (PMID 40610400, 2025). "Anemia was observed in recipients of pig-to-NHP kidney xenotransplants and was probably due to the molecular incompatibility between pig erythropoietin (Epo) and the primate Epo receptor." (PMID 40026598, 2025). "This newly marketed drug increases the concentration of erythropoietin in the kidney and liver to the physiological range so as to increase or maintain the Hb concentration in CKD patients with anemia." (PMID 40000368, 2025). "Various factors contribute to anemia in CKD, with the most significant being a relative shortage of erythropoietin (EPO)." (PMID 39958087, 2025). "Recombinant human erythropoietin (rHuEPO), a 30-kDa protein therapeutic drug, was approved by the FDA in 1989, and it is being used to treat anemia due to chronic kidney disease or chemotherapy." (PMID 39849218, 2025). "AI has also shown promise in optimizing drug prescriptions, such as erythropoietin dosing for anemia management in patients with ESKD, where it has reduced hemoglobin variability and erythropoietin dosage." (PMID 39981468, 2025).
anemia (continued). "Anemia is another common manifestation of CKD, arising mainly from reduced erythropoietin production and disordered iron metabolism." (PMID 41155502, 2025). "This triggers a cascade of gene expressions related to hypoxia adaptation, boosts endogenous erythropoietin (EPO) production, elevates hemoglobin levels, and ameliorates anemia." (PMID 38962312, 2024). "In recent years, erythropoietin (EPO) therapy, traditionally used for managing anaemia in various clinical contexts, has emerged as a potential breakthrough in the treatment of SCA." (PMID 38463100, 2024). "Recombinant human erythropoietin (EPO) has important therapeutic applications, for example in treating anemia in chronic kidney disease and cancer." (PMID 38254725, 2024). "EPO and darbepoetin alfa (DPO) are two ESAs commonly utilized interchangeably for managing anemia in CKD patients, including those with ESRD necessitating dialysis." (PMID 38313992, 2024). "Because anemia is common in patients with CKD due to reduced kidney erythropoietin production, our findings suggest the late reduction in hemoglobin and RBC after [212Pb]Pb-MC1L treatment was secondary to anemia of CKD." (PMID 38095674, 2024). "Anemia, one of the significant clinical findings presented in MDS patients, is commonly treated with blood transfusions and erythropoietin." (PMID 38508444, 2024). "Studies have also shown anemia, a derangement in hemoglobin, to result as a consequence of AKI due to progressively falling levels of erythropoietin." (PMID 39398773, 2024). "Two studies addressed patients receiving erythropoietin for CKD anemia, while one study investigated anemia due to gastrointestinal bleeding." (PMID 39338353, 2024). "Research reports that SXN can effectively stimulate red blood cell production by promoting erythropoietin (EPO) synthesis and regulating iron homeostasis in adenine-induced anemia." (PMID 39334913, 2024). "This trial compares the efficacy of EPO and hydroxyurea, a standard treatment for SCA, in improving anaemia and clinical outcomes." (PMID 38463100, 2024). "Though erythropoietin therapy is the mainstay of CKD-induced anemia, a significant CKD patients are refractory to erythropoietin (EPO) effects due to inflammation, deranged iron utilization, and generation of EPO antibodies." (PMID 39502472, 2024). "TGF-β superfamily inhibitors can both ameliorate CEC suppressive effects and cooperate with EPO to promote RBC production and alleviate anemia; neutralization of TGF-β also reduces CEC expansion." (PMID 39474425, 2024). "However, in terms of clinical relevance, small deviations might be considered less critical for the diagnostic assessment and the resulting therapeutic consequence in patients because, in anemia diagnostics, the level of EPO in combination with other relevant biomarkers is of decisive importance." (PMID 38974321, 2024). "EPO therapy exerts multifaceted effects on CKD, including the correction of anemia, tissue protection, anti-inflammatory actions, and mitigation of ischemia-reperfusion injury." (PMID 39200211, 2024). "In cases of anemia or hypoxia, HIF binds to the erythropoietin (EPO) 5’ hypoxia response element, resulting in increased EPO gene transcription." (PMID 39408813, 2024). "Anemia, common in CKD due to reduced erythropoietin production, decreases oxygen delivery to the myocardium, leading to LVH and failure as the heart attempts to compensate." (PMID 39398794, 2024). "Also, renal failure may lead to impaired production of erythropoietin and anaemia." (PMID 38424178, 2024). "Anemia is highly prevalent in patients with chronic kidney disease (CKD), primarily due to diminished erythropoietin synthesis." (PMID 39768541, 2024). "Since the plasma concentration of several proteins lost in the urine but not secreted by the liver, such as erythropoietin (EPO) and IgG, is not defended by increased synthesis, urinary loss of these proteins may cause reduced immunity, anemia, and deficiency syndromes." (PMID 38393003, 2024).
anemia (continued). "Anemia is common in CKD patients,primarily due to diminished erythropoietin production, inadequate hematopoieticraw materials, and a metabolically disordered internal environment unfavorablefor red blood cell growth." (PMID 39742232, 2024). "JPYS enhanced red blood cells (RBCs), hemoglobin (HGB), and hematocrit (HCT) levels by triggering the expressions of EPO and hypoxia-inducible factor-2 alpha (HIF-2α) proteins in rats with anemia induced by 5/6 nephrectomy." (PMID 39911241, 2024). "They stimulate alterations in erythroid progenitor proliferation, erythropoietin (EPO) synthesis, survival of circulating erythrocytes, iron balance, redox state and energy metabolism, all of which can contribute to anemia." (PMID 38337488, 2024). "Although administration of erythropoietin therapy decreased in both groups (only significantly in the CKD group), the incidence of anemia declined significantly in both groups over time." (PMID 38850407, 2024). "The benefit of PHD inhibitors (PHDi) in the treatment of anemia and lactatemia arises from HIF stabilization, which stimulates endogenous production of erythropoietin and activates lactate recycling through gluconeogenesis." (PMID 38365865, 2024). "Tests for assessing anemia (Iron, TIBC, Ferritin, EPO) were performed more frequently during the progressive CKD and proteinuria stages." (PMID 38431648, 2024). "Anemia is a frequent complication in patients with CKD and is a result of both decreased erythropoietin (EPO) production by kidney peritubular fibroblasts and iron deficiency." (PMID 36831276, 2023). "Erythropoietin (EPO), preoperative autologous blood donation (PAD) and oral iron are commonly discussed modalities for managing preoperative anemia." (PMID 36691071, 2023). "Recombinant erythropoietin (EPO) and darbepoetin (DARBO) are the first-line agents used for treating anemia in LR MDS patients who have serum EPO (sEPO) levels ≤ 500 U/L." (PMID 37504319, 2023). "It increases the erythropoietin concentration within physiologic range in the liver and kidneys, thereby increasing or maintaining the hemoglobin concentration in CKD patients with anemia." (PMID 36910473, 2023). "Using medical subject heading (MeSH) terms and straightforward keyword combinations (such as "anemia," "CKD," "HIF-PHI," "EPO stimulating agents," "safety," and "efficacy"), relevant literature was retrieved." (PMID 38021836, 2023). "Anemia is a known complication of CKD and results primarily from decreased erythropoietin synthesis in the kidney." (PMID 36979469, 2023). "The mechanisms of anemia in CKD are multifactorial and include inhibited erythropoietin production by the kidney, shortened lifespan of red blood cells, iron deficiency, and chronic inflammation." (PMID 36983703, 2023). "By taking oral iron supplements or subcutaneous erythropoietin, the patients were already taking preventive measures against CKD-induced anemia." (PMID 37868481, 2023). "However, in another study, it was reported that 70% of anemic patients without compromised renal function also had reduced EPO levels, suggesting that the likelihood of functional EPO deficiency related to anemia is independent of the severity of renal failure." (PMID 37606388, 2023). "CKD-related anemia results when the glomerular filtration rate (GFR) is less than 60 ml/min, and the kidney is unable to generate enough EPO in response to hypoxia." (PMID 38021836, 2023). "Due to the relatively inadequate production of erythropoietin (EPO) in patients with chronic kidney disease, anemia is highly prevalent in this population." (PMID 37791567, 2023). "Recombinant human erythropoietin (rHuEPO) in its native and re-engineered forms is used as a therapeutic to alleviate CKD-induced anemia by stimulating erythropoiesis." (PMID 38125882, 2023). "Serum EPO levels are higher in CKD and HF patients but disproportionately low for the degree of anemia." (PMID 37374094, 2023).
anemia (continued). "TBP, MAPK1, and RPP30 are the most stable genes that are uninterrupted by anemia, OIR and EPO administration." (PMID 37098032, 2023). "On the other hand, anemia is common in patients with CKD, and targeted therapy against it, for example, erythropoietin (EPO)–stimulating agent treatment, can induce increased FGF23 serum levels." (PMID 35966090, 2022). "Anemia is a common complication of CKD, mainly due to injured kidneys failing to produce sufficient amounts of EPO, which regulates red blood cell production." (PMID 36364144, 2022). "Current therapies used to treat anemia in CKD include blood transfusions, intravenous iron therapies, or parenteral injections of recombinant erythropoietin (rhEPO)." (PMID 36055212, 2022). "Because anemia is common in DM patients with CKD, using EPO prescription as a proxy for advanced CKD was reasonable." (PMID 35355728, 2022). "The principal reason for anemia in CKD patients is the accumulation of uremic toxins, which suppress erythropoietin production by renal interstitial fibroblasts." (PMID 35746954, 2022). "When studies began reporting on the CNS effects of EPO in the late 1990s, it was already an FDA approved (in 1989) anemia drug." (PMID 36081576, 2022). "Erythropoietin (Epo), a key growth factor for RBC production (erythropoiesis), is frequently used for the treatment of anemia." (PMID 35740448, 2022). "Roxadustat treats anemia through multiple pathways, not only by activating HIF to increase EPO levels but also by decreasing hepcidin levels and reducing inflammation." (PMID 35535500, 2022). "Previously it has been shown that in a mouse inflammation model EPO stimulates spleen BMP4-dependent stress-induced erythropoiesis and reduces anemia." (PMID 36457703, 2022). "Inhibition of HIF-PH by molidustat, which is used for the treatment of renal anemia, leads to activation of the HIF pathway and increased expression of erythropoietin downstream of the HIF pathway, thereby improving anemia." (PMID 35745653, 2022). "In this CDDP-induced model, TBN effectively relieved the symptoms of anemia and increased the levels of the RBC count, HCT, Hb and EPO." (PMID 36324690, 2022). "In an effort to promote angiogenesis after nerve injury, we used erythropoietin (EPO), a pleiotropic hormone approved by the U.S. Food and Drug Administration (FDA) for anemia treatment." (PMID 36307805, 2022). "Of note, 36% (10/28) of them showed mild degree of anemia and slightly increased levels of ERFE despite the high EPO levels." (PMID 35163229, 2022). "In terms of hematologic factors, repeated blood transfusions, erythropoietin (EPO) levels, and anemia are interlinked in terms of pathogenicity." (PMID 36589197, 2022). "The pathogenesis of anemia in CKD is multifactorial, but decreased erythropoietin production is a main contributing factor." (PMID 35043997, 2022). "Although defects in EPO and iron handling have been described as important features of CKD involved in anemia development, several other factors have also been suggested." (PMID 36432528, 2022). "HMGB1 has been shown to significantly attenuate erythropoietin (EPO)-mediated phosphorylation of the JAK2/STAT5 and mTOR signaling pathways, contributing to the chronic phase of anemia of inflammation." (PMID 35961978, 2022). "A previous study reported that erythropoietin production is increased in a compensatory manner in PARP-2-/- mice and contributes to the maintenance of erythropoiesis, thus suggesting that erythropoietin may have an effect on ameliorating the risk of severe anemia." (PMID 36267984, 2022). "In addition to hypoxia, EPO production could be induced in response to a number of other challenges or instants including anemia, high altitude, mechanical damage, infection, metabolic stress, elevated temperature, intense neural activity, enriched environment, and ischemic stress." (PMID 35250554, 2022).